EGFR (epidermal growth factor receptor)
Diseases named in the same sentence as EGFR in open-access papers (continued):
Sharing a sentence is not in itself a finding about the gene and the disease.
Hypertension (110 papers, 2009 to 2026). The presence of chronic increased pressure in the systemic arterial system. "Before initiating treatment with EGFR-TKIs, a rigorous baseline risk assessment must be performed on all patients, and baseline cardiovascular risk factors, including obesity, diabetes, hypertension, smoking, etc., must be carefully considered." (PMID 38983928, 2024). "While the direct causative link between EGFR-TKI drugs in isolation and hypertension remains uncertain, existing evidence suggests the involvement of EGFR/ErbB1 in vascular remodeling." (PMID 39211774, 2024). "The risk of grade 3 AEs and higher hypertension and proteinuria were greater in patients treated with the EGFR-TKIs plus bevacizumab combination." (PMID 38539522, 2024). "Hypertension, a prevalent cardiovascular risk factor and a possible side effect of EGFR-TKIs, demands serious attention from clinicians." (PMID 39211774, 2024). "But EGFR inhibitors were reported to be associated with an increased risk of hypertension and QT interval prolongation, while ALK inhibitors were linked to bradycardia and QT prolongation." (PMID 39766122, 2024). "Nevertheless, the combination of antiangiogenic agents with EGFR‐TKIs had the highest risk of grade ≥3 hypertension and proteinuria." (PMID 36594109, 2023). "EGFR has been associated not only with vascular homeostasis but also with diverse pathologies, including cardiovascular diseases such as hypertension or atherosclerosis, in which it appears mostly harmful." (PMID 38129563, 2023). "VEGFR and EGFR inhibitors have recently been described in the literature to cause hypertension, proteinuria, and glomerular endotheliosis." (PMID 35870899, 2022). "With respect to the existence of comorbidities, hypertension happened to be the highest comorbidity among EGFR mutated patients in our and the Levant population." (PMID 34963835, 2021). "This is clinically relevant because anticancer EGFR tyrosine kinase inhibitors cause hypomagnesemia and hypertension." (PMID 32706027, 2020). "ADAM17 also cleaves most of the ligands of the epidermal growth factor receptor (EGFR) which have been associated with hypertension, atherogenesis, vascular dysfunction, and cardiac remodeling." (PMID 33330676, 2020). "This interplay may be particularly important in conditions associated with EGFR hyperactivation, perturbed cation (Mg2+) regulation and vascular dysfunction, such as in hypertension and other cardiovascular diseases." (PMID 32706027, 2020). "Our study showed that Apatinib could have the adverse effect of causing hypertension (38.50%), hand-foot syndrome (46.20%), and proteinuria (18.00%) in the treatment of advanced progressed LA with EGFR-TKI resistance." (PMID 31570733, 2019). "We assessed the toxicities of rash and cough mainly caused by targeting EGFR, toxicity of hypertension mainly caused by targeting VEGFR, and other common toxicities occurred in the routine chemotherapy procedure, for example, the diarrhea, nausea, vomiting and anemia." (PMID 23861835, 2013). "As microvascular damage and hypertension are strongly associated with intermittent ischemia, hypoxia, and AD-related pathology, it seems likely that the cerebrovascular activity of the EGFR is an important aspect of its role in neurodegenerative pathophysiology." (PMID 22754566, 2012). "This can result in a range of toxic side effects, including hyperglycemia with PI3K inhibition, hypertension with vascular endothelial growth factor inhibition, and skin rash with EGFR inhibition." (PMID 37568193, 2023). "Hypertension and proteinuria were substantially increased in patients treated with angiogenesis inhibitors and EGFR‐TKIs (hypertension: RR = 4.88, 95% CI: 3.49–6.81, p < 0.001; proteinuria: RR = 12.83, 95% CI: 3.98–41.38, p < 0.001)." (PMID 36594109, 2023).
Hypertension (continued). "For example, EGF via stimulation of EGFR elicited potent vasoconstriction in aortic strips from a rat model of hypertension; and EGFR activation via MMP-2 reportedly increased ROS formation and facilitated contraction in non-diabetic aortas." (PMID 34408653, 2021). "It has been shown that in vivo application of EGFR inhibitors or antisense oligonucleotides can prevent hypertension and cardiac hypertrophy in different animal models." (PMID 34168192, 2021). "Future studies are needed to further investigate the outcomes of hypertension upon the combination of EGFR and/or VEGFR/PDGFR inhibition." (PMID 32413049, 2020). "Diarrhea and skin toxicity are the most common AEs of EGFR-TKIs35, while hypertension, proteinuria, hemorrhage and arterial thromboembolic events are the most common AEs in patients treated with angiogenesis inhibitors." (PMID 31942192, 2020). "Inhibition of EGFR and its downstream signaling targets ameliorate endothelial dysfunction and vascular remodeling in experimental models of hypertension." (PMID 32706027, 2020). "Upregulation of TRPC3 induces in cerebrovascular remodeling during hypertension via transactivation of epidermal growth factor receptor- (EGFR-) dependent signaling pathways." (PMID 31871548, 2019). "Researchers also found that upregulation of TPRC3 enhances EGFR transactivation, which is involved in hypertension-induced cerebrovascular remodeling by the signaling pathway TRPC3/ADAM17." (PMID 31871548, 2019). "Activation of EGFR is known to be involved in many pathological processes such as endothelial dysfunction, hypertension, restenosis, atherogenesis, and cardiac remodeling." (PMID 29686623, 2018). "EGFR transactivation has been implied in several cardiovascular conditions, including hypertension, heart failure, and cardiac and vascular hypertrophy." (PMID 30046277, 2018). "In models of experimental hypertension, EGFR blockers reduced blood pressure elevation and improved vascular lesions." (PMID 30670929, 2018). "The occurrence of specific AEs has been shown to predict better treatment responses both in target and endocrine therapy, such as rash induced by EGFR inhibitors, hypertension after sunitinib treatment and arthralgia/myalgia in exemestane treated patients." (PMID 28938684, 2017). "Hypertension and vascular events were observed with anti-angiogenetic agents, while skin toxicities were reported with anti-EGFR agents according to Literature data." (PMID 27764790, 2016). "It has been demonstrated that transactivation of EGFR by Ang II led to vascular resistance and high blood pressure, and EGFR inhibition by AG1478 has been shown to prevent Ang II‐induced hypertension." (PMID 26762600, 2016). "As alterations in VSMC tone and function are likely to affect systemic hypertension, it is interesting to note that elevated plasma glucose can also result in the transactivation of the EGFR in renal disorders." (PMID 22754566, 2012). "The nephrectomy/aldosterone/salt treatment (thereafter called NAS) induces hypertension and cardiovascular remodelling and was used to evaluate the response of mice with defective EGFR signalling to chronic aldosterone challenge." (PMID 22291909, 2012). "Second, increased expression and/or activity of EGFR were reported in various experimental models of hypertension, and EGFR inhibitors reduce blood pressure in some of these models." (PMID 21286276, 2010). "Vandetanib has additional activity versus EGFR and the adverse event profile of vandetanib in this and previous studies is consistent with pharmacodynamic inhibition of both VEGFR (hypertension) and EGFR signaling (rash, diarrhea)." (PMID 19946413, 2009). "However, its affinity for Cys481 cysteine residues in kinases such as those from the Tec family, epidermal growth factor receptor, and Janus kinase leads to off-target effects, contributing to adverse events like atrial fibrillation and hypertension." (PMID 40263985, 2025).
Hypertension (continued). "Beyond immune regulation, it also contributes to cardiovascular disease-related pathways by mediating the cleavage of epidermal growth factor receptor (EGFR) ligands, which are implicated in the pathogenesis of conditions such as coronary artery disease, aneurysm, heart failure, and hypertension." (PMID 41050403, 2025). "Similarly, vascular oxidative stress contributes to endothelial dysfunction in hypertension through pathways involving EGFR and proinflammatory kinases." (PMID 40909129, 2025). "Thus, further studies are needed to ascertain the relative contribution of EGFR in mediating hypertension versus its direct effects on kidney damage per se." (PMID 39234105, 2024). "In addition, inhibition of EGFR also reduced vasoconstriction and improved blood pressure in models of hypertension." (PMID 39234105, 2024). "Similar efficacy-toxicity relationships have emerged for molecularly targeted therapies, including better outcomes in the setting of high-grade cutaneous reactions from epidermal growth factor receptor (EGFR) inhibitors or hypertension from antiangiogenic agents." (PMID 38690281, 2024). "It is known that EGFR expression is elevated in the vascular smooth muscle cells from hypertensive rats and in atherosclerotic plaques that may have an impact on hypertension." (PMID 39234105, 2024). "Moreover, inhibition of epidermal growth factor receptor (EGFR) activity is emerging as a potential treatment for hypertension." (PMID 35360657, 2022). "The incidence of hypertension, hand-foot syndrome, and fatigue was compared in detail between the EGFR mutation and EGFR negative groups." (PMID 35524294, 2022). "The activation of EGFR promotes VSMCs proliferation, migration, inflammation and fibrosis, and participates in the process of vascular remodeling in vascular diseases (such as hypertension and atherosclerosis)." (PMID 35656112, 2022). "EGFR was also involved in Ang II-induced cardiac hypertrophy and hypertension." (PMID 34439742, 2021). "It was suggested that EGFR signaling is enhanced in various animal models of hypertension." (PMID 34627325, 2021). "EGFR is expressed in the vascular wall and myocardium, and EGFR transactivation may contribute to arterial hypertension due to abnormal regulation of vascular tone." (PMID 34564376, 2021). "In this meta-analysis, rash (16.6%), hypertension (14.7%) and diarrhea (13.3%) were the most common AEs in the combination group, while rash (11.5%), anemia (3.8%) and fatigue (3.4%) were common in the EGFR-TKI alone group." (PMID 31942192, 2020). "It has been more recently reported that EGFR activation may contribute to the development of hypertension by regulating vascular tone and renal sodium handling." (PMID 23533381, 2013). "Hence EGFR inhibitors have been used to reduce blood pressure in experimental models of hypertension, suggesting that EGFR is a novel target for salt sensitive hypertension." (PMID 23533381, 2013). "Transactivation of EGFR by these factors has been observed in blood vessels and the kidney and may contribute to the development of arterial hypertension by increasing vascular tone and/or tubular Na+ reabsorption." (PMID 23577024, 2013). "Several lines of evidence suggest the role of EGFR in arterial hypertension." (PMID 21286276, 2010). "Since the advent of EGFR-TKI drugs, their associated cardiovascular adverse events have been extensively documented, including prolonged QT intervals, HF, atrial fibrillation (AF), myocardial infarction (MI), pericardial effusion, hypertension, and cardiac valvular lesions." (PMID 39211774, 2024). "Furthermore, adult COVID-19 patients with hypertension may more frequently and easily progress from the propagation phase to the complication phase due to alterations in the EGFR and IGF2R genes." (PMID 38813031, 2023).
Hypertension (continued). "Although anti-angiogenic agents combined with EGFR-TKIs demonstrated beneficial effects for PFS in our meta-analysis, anti-angiogenic agents may also cause adverse reactions, such as epistaxis, hypertension, proteinuria, bleeding, and tracheoesophageal fistula." (PMID 35743437, 2022). "However, grade ≥ 3 AEs were more frequent in patients treated with angiogenesis inhibitors and included hypertension, hemorrhage and proteinuria for anti-angiogenic-induced events, and neutropenia, thrombocytopenia, diarrhea and fatigue for EGFR-TKIs induced events." (PMID 31942192, 2020). "The most frequent treatment-related grade ≥ 2 adverse events likely related to the EGFR inhibition by cetuximab and erlotinib were: rash (56%), hypomagnesemia (17%), pruritus (11%), diarrhea (8%) and likely related to antiangiogenic effect of bevacizumab were: hypertension, bleeding, and fistula." (PMID 32337094, 2020). "Network pharmacology identified ten key bioactive compounds (e.g., liquiritigenin, isoliquiritigenin, and caffeic acid), 149 hypertension-related targets, and ten core targets such as SRC, PIK3CA, PIK3CB, EGFR, and IGF1R." (PMID 41155608, 2025). "In conclusion, our study demonstrated that the addition of bevacizumab or ramucirumab to an EGFR‐TKI as a front‐line treatment provided similar PFS and OS, while ramucirumab user had significantly high‐grade hypertension." (PMID 38523603, 2024). "Our results indicated that the most common adverse reactions in patients receiving Apatinib combined with EGFR-TKI treatment are diarrhea and hypertension." (PMID 39281226, 2024). "The most common adverse events were rash (n = 9, 37.5%), diarrhea (n = 6, 25.0%) related to EGFR–TKI and hypertension (n = 6, 25.0%) related to anlotinib, followed by transaminase elevation (n = 4, 16.7%) and fatigue (n = 4, 16.7%)." (PMID 34510760, 2021). "Activation of EGFR promotes VSMC proliferation, migration, inflammation and fibrosis, processes involved in vascular remodeling in cardiovascular diseases such as hypertension and atherosclerosis." (PMID 32706027, 2020). "Other toxicities were as expected for a combination of EGFR and VEGFR inhibition, including PPES and hypertension." (PMID 28352985, 2017). "All subpopulations of statin users stratified by sex, age, DM, hypertension, stroke, CAD, COPD, smoking-related disorder, CT/RT, EGFR-TKIs, EGFR-TKI response, and CT regimens before EGFR-TKI had a significantly reduced risk of death (p < 0.001)." (PMID 28158206, 2017). "Vandetanib, a dual VEGFR and EGFR inhibitor, yielded an improvement in PFS but more frequent grade 3 or greater hypertension." (PMID 27329593, 2016). "Vandetanib, an approved EGFR inhibitor for medullary thyroid cancer, targets EGFR, VEGFR, and RET, offering broad efficacy, but is limited by adverse effects like diarrhea, rash, nausea, hypertension, and QT prolongation." (PMID 40872743, 2025). "On the other hand, EGFR is expressed in collecting ducts as well as in vascular cells, and infusion of EGF decreases epithelial sodium channel (ENaC) activity and prevents the development of hypertension and glomerular and tubular damage in Dahl SS rat strain." (PMID 40165104, 2025). "Combined with protein interaction network analysis, the potential primary targets of berberine in treating hypertension may include AKT1, BCL2, EGFR, STAT3, and TNF." (PMID 41567631, 2025). "In our study, we also showed that the occurrence of hypertension has important significance in guiding prognostication for elder patients with EGFR negative NSCLC." (PMID 35524294, 2022). "The most common EGFR-TKI–related adverse events were dermatitis acneiform and paronychia, whereas the most common anti-angiogenesis–related adverse events were proteinuria (21.7%) and hypertension (18.3%)." (PMID 35599308, 2022).
Hypertension (continued). "Combination therapy consisting of an anti-angiogenesis drug and an EGFR-TKI increased the incidence of adverse events of any grade compared with EGFR-TKI therapy alone, especially proteinuria (21.7%), hypertension (18.3%), and bleeding (11.7%), consistent with previous real-world studies." (PMID 35599308, 2022). "The incidence of hypertension was 50% (19/38), and PFS significantly differed between patients with and without hypertension during anlotinib treatment in the EGFR gene negative group." (PMID 35524294, 2022). "On the other hand, other TKIs such as vatalanib and gefitinib (respective VEGFR and EGFR inhibitors) did not induce hypertension in treated mice." (PMID 32698382, 2020). "In addition, this study describes for the first time the increased activation of the EGFR and its downstream signaling pathways in rat mesenteric arteries after long period post-orchidectomy, that maintained for prolonged periods of time could contribute to the development of hypertension." (PMID 25013941, 2014). "In the present study we reported the activation of the EGFR in mesenteric arteries after long period post-orchidectomy, and the animals did not develop hypertension, probably due to the existence of compensatory mechanisms." (PMID 25013941, 2014). "Indeed, EGFR inhibitors such as AG1478 reduce vascular tone and blood pressure in several experimental models of hypertension." (PMID 23577024, 2013). "The most frequently reported grade 3 or worse TRAEs included hypertension (12.0%), γ-glutamyl transferase increased (5.0%) and hyponatremia (5.0%) in the EGFR TKI plus anlotinib group and dry skin, paronychia and appetite decreased, each occurring in 8.0% patients in the EGFR TKI group." (PMID 41282608, 2025). "Moreover, atezolizumab plus bevacizumab plus chemotherapy showed significant improvements in PFS and OS in EGFR TKI-resistant patients; however, the incidence of adverse reactions was higher, especially for antiangiogenesis-related AEs such as hypertension and proteinuria." (PMID 37951898, 2023). "Most EGFR, SRC (including dasatinib), RAF (such as BRAF inhibitor HG-6-64-01), and MEK inhibitors displayed antiviral effects, while the majority of hormones, steroid hormones, immunomodulators and various drugs used to treat hypertension or heart conditions showed distinct antifibrotic scores." (PMID 34045585, 2021). "‘Unknown I’ contained a diverse set of key driver genes such as SGK1, SIK1 and SLC10A6 (sodium metabolism and hypertension), MT2A and TSC22D3 (glucocorticoid signaling), GADD45G, ERRFI1, GPRC5A, and EGFR (cell growth and apoptosis), and CEBPB, CEBPD, and KCNA5 (heart development and function)." (PMID 25033284, 2014).